FTX (FTX transcript, XIST regulator)
Diseases named in the same sentence as FTX in open-access papers (continued):
Sharing a sentence is not in itself a finding about the gene and the disease.
cervical cancer (2 papers, 2020 to 2021). A primary or metastatic malignant neoplasm involving the cervix. "In the course of our research, reports demonstrated that lncRNA CASC2 sponges miR-21 in oral squamous cell carcinoma and in the modulation of sensitizes cervical cancer to cisplatin, and lncRNA FTX can also negatively control miR-21-5p during status epilepticus." (PMID 33203802, 2020).
lymph node metastasis (2 papers, 2021 to 2023). "The results showed that higher expression of FTX was significantly correlated with poor differentiation (P = 0.048), lymph node metastasis (P = 0.041), and clinical stage (P = 0.034)." (PMID 37993428, 2023).
non-alcoholic fatty liver disease (2 papers, 2020 to 2024). "Downregulation of lncRNA five prime to Xist (FTX) and overexpression of lncRNA small nucleolar RNA host gene 20 (SNHG20) promoted the development of nonalcoholic fatty liver disease (NAFLD) into HCC by modulating the polarization of Kupffer cells." (PMID 38405061, 2024).
uveal melanoma (2 papers, 2020 to 2021). A melanoma derived from melanocytes of the uveal tract. "In addition, one previous study found that FTX was also associated with the progression of uveal melanoma (UM), which is another intraocular malignant tumor." (PMID 34720057, 2021). "We previously reported that lncRNA CANT1 triggers a CANT1-JPX/FTX-XIST long noncoding pathway to suppress uveal melanoma progression." (PMID 32366932, 2020). "One previous study demonstrated that FTX might play a potential role in uveal melanoma (UM), also an intraocular malignant tumor." (PMID 34720057, 2021).
asthma (1 paper, 2024). "Similarly, lncRNA FTX sponges miR590-5p to upregulate the JAK2 signaling pathway, aggravating asthma." (PMID 39595622, 2024).
Cerebral ischemia (1 paper, 2025). Restriction of arterial blood supply to the brain associated with insufficient oxygenation to support the metabolic requirements of the tissue. "Notably, lncRNA FTX inhibits ferroptosis in magnesium-free-induced hippocampal neurons via the miR-142-5p/GABPB1 axis and protects against cerebral ischemia–reperfusion injury by enhancing neuronal proliferation and reducing apoptosis through the miR-186-5p/MDM4 pathway." (PMID 40725099, 2025).
cognitive decline (1 paper, 2025). "These genes conferred both risk and protection, with greater MCF2 and FTX expression associated with less tau tangles in females and slower cognitive decline in males, respectively." (PMID 40166028, 2025). "When focusing on X-linked genes, sex significantly moderated MCF2, HDAC8, SLC10A3, and FTX on tau tangle burden or cognitive decline in the DLPFC." (PMID 40166028, 2025). "We observed a significant APOE-ε4 x sex x FTX interaction on longitudinal cognition (p = 0.03), whereby the male-specific protective effect of FTX expression on cognitive decline was driven by APOE-ε4 carriers (β = 0.05, p = 0.01)." (PMID 40166028, 2025).
diabetes (1 paper, 2023). "Therefore, it is possible that FTX is involved in the inflammatory response in diabetes through MIF." (PMID 36874406, 2023).
lentivirus infection (1 paper, 2020). Virus diseases caused by the Lentivirus genus. "Furthermore, the expression of FTX was significantly downregulated in liver tissues from NAFLD-HCC mouse, but lentivirus infection effectively increased the expression of FTX." (PMID 32595415, 2020).
lobular carcinoma (1 paper, 2022). "The expression of AC078883.1 and ADAMTS9-AS1 were significantly decreased, while the expression of the AL035661.1, CBR3-AS1, FTX, and TMEM105 were significantly increased in the patient with breast infiltrating duct and lobular carcinoma with high-risk value." (PMID 35444943, 2022). "Finally, we found that AC007686.3, AC078883.1, ADAMTS9-AS1, AL035661.1, CBR3-AS1, FTX, and TMEM105 were significantly associated with the OS of patients with breast infiltrating duct and lobular carcinoma." (PMID 35444943, 2022). "We found that seven ferroptosis- and immune-related differentially expressed lncRNAs (FI-DELs) (AC007686.3, AC078883.1, ADAMTS9-AS1, AL035661.1, CBR3-AS1, FTX, and TMEM105) were correlated with the overall survival of patients with breast infiltrating duct and lobular carcinoma." (PMID 35444943, 2022).
metastatic tumors (1 paper, 2023). "lncRNA regulation occurs throughout tumor development, during the early stages such as SNGH11; in advanced stages, for example, MFI2-AS1; and even in metastatic tumors with both pro- and anti-tumoral effects, such as FTX and NBR2, respectively." (PMID 38132443, 2023).
ovarian tumors (1 paper, 2024). "We also found that XIST downregulation was associated with lower levels of its activators, JPX and FTX, in ovarian tumors." (PMID 39546568, 2024). "Downregulation of XIST in ovarian tumors is associated with reduced expression of upstream activators JPX and FTX." (PMID 39546568, 2024).
retinoblastoma (1 paper, 2021). A malignant tumor that originates in the nuclear layer of the retina. "Long non-coding RNA (lncRNA) five prime to Xist (FTX) exerts important functions in human cancer, while its role in retinoblastoma (RB) remains unclear." (PMID 34720057, 2021).
rheumatoid arthritis (1 paper, 2022). A chronic, systemic autoimmune disorder characterized by inflammation in the synovial membranes and articular surfaces. "Modulating both microRNAs and gene expression, FTX may affect a lot in pathogenesis of rheumatoid arthritis, which as one of chronic inflammatory autoimmune disease." (PMID 35725478, 2022).
serous ovarian carcinoma (1 paper, 2021). "Two immune-related lncRNAs, FTX and LINC00665, were identified as prognostic biomarkers in high-grade serous ovarian carcinoma." (PMID 33997040, 2021).
skin cutaneous melanoma (1 paper, 2024). "We analyzed TCGA data and found that pre-miR-545 was substantially negatively correlated with FTX in three tumor types (KICH, MESO, and UCS) but was substantially positively correlated with FTX in skin cutaneous melanoma." (PMID 39027151, 2024).
thymoma (1 paper, 2024). A neoplasm arising from the epithelial cells of the thymus. "miR-545-3p expression was upregulated in uterine corpus endometrial carcinoma (UCEC) and markedly negatively correlated with FTX in three tumor types: MESO, rectum adenocarcinoma (READ), and thymoma (THYM)." (PMID 39027151, 2024).
tumor (31 papers, 2019 to 2025). "FTX has been implicated in tumor cell proliferation and migration, though its function varies by tissue and cancer type." (PMID 40342081, 2025). "Several lncRNAs with abundant expression (LRRC75A-AS1, HYMAI, NEAT1, XIST and FTX) were closely associated with tumor size, which may suggest to be biomarkers for the GIST malignancy." (PMID 34557343, 2021). "We also identified five lncRNAs with abundant expression (LRRC75A-AS1, HYMAI, NEAT1, XIST and FTX) were closely associated with tumor progression, which may suggest to be the biomarker for the malignancy of GIST." (PMID 34557343, 2021). "In this research, the expression of Lnc-FTX in tumor and adjacent non-tumor liver tissues from HCC patients were examined, and its impact on the malignant phenotype of HCC cells was investigated." (PMID 40084261, 2025). "The abnormal expression of Lnc-FTX exhibits tissue heterogeneity, and the molecular mechanism of tumor regulation needs to be further investigated." (PMID 40084261, 2025). "In the HCC setting, LncRNA FTX acts as a tumor suppressor, inhibiting HCC cell growth and metastasis." (PMID 37508414, 2023). "Lastly, a group of cells, emerged as specifically expressing non‐coding RNAs with a tumor‐associated role, such as MEG3, NEAT1, and FTX (Fig EV5C and D)." (PMID 38037472, 2023). "In conclusion, our study showed for the first time that a distinct cancer-promoting CAF subset, PDPN+ CAFs, secrete exosomal lncRNA FTX in the tumor microenvironment." (PMID 37993428, 2023). "Integrative analysis of tumor-infiltrating CD8+ T-cell abundance and overexpressed oncogene candidates showed that MCL cases with high ratio CD8+ T-cells and low expression of FTX or PCA3 can potentially predict high-risk MCL patients." (PMID 36359790, 2022). "In this study, the effects of FTX on PC tumor growth in vivo were investigated by establishing xenotransplantation mouse model." (PMID 33736615, 2021). "In vivo experiments further confirmed that knockdown of FTX efficiently prevents tumor growth in vivo." (PMID 34720057, 2021). "The xenotransplantation mouse model was established to explore the effect of FTX and miR-513b-5p on the PC tumor growth in vivo." (PMID 33736615, 2021). "The expression of HYMAI, NEAT1, XIST and FTX were negatively correlated with tumor diameter and significantly down-regulated during GIST progression." (PMID 34557343, 2021). "All in all, our data demonstrated that the expression of FTX and the ratio of M1/M2 KCs were decreased in tumor tissues of NAFLD-HCC." (PMID 32595415, 2020). "Similar to our results, a significant decrease of FTX in HCC tissues was observed, and patients with higher FTX expression exhibited longer survival, it acted as a tumor suppressor through binding with miR-374a and MCM2." (PMID 32419983, 2020). "In a same mouse, tumour derived from FTX‐OE A549 cells developed more slowly than the one from control A549 cells." (PMID 32176463, 2020). "Next, we revealed that increasing of FTX effectively repressed the growth of tumor and improved the liver damage in NAFLD-HCC, thus to inhibit the progression of NAFLD to HCC." (PMID 32595415, 2020). "Overall, overexpression of FTX significantly inhibited the growth of tumor and improved the liver damage during NAFLD conversion to HCC via promoting KCs polarization to M1 phenotype." (PMID 32595415, 2020). "Thus, the higher number of patients in lower TNM stages in our cohort likely explains the increased prevalence of lower Lnc-FTX expression in tumor tissues." (PMID 40084261, 2025). "Additionally, PDPN+ CAFs transport the exosomal lncRNA FTX to tumor cells, activating the FTX–FEN1–ACSL4 axis to inhibit ferroptosis and potentiate invasiveness." (PMID 41430036, 2025). "Both FTX and miR-545-3p are upregulated and exhibit tumor-promoting functions in CRC." (PMID 39027151, 2024).
tumor (continued). "Therefore, it is crucial to consider the unique chromosomal locations of FTX and miR-545, as well as their potential sex-specific implications in tumor diagnosis and treatment." (PMID 39027151, 2024). "The different roles of FTX indicate its unique regulation in various tumor cells." (PMID 37106382, 2023). "Moreover, we found that the expression of FTX was increased in 29 of 32 (90.6%) fresh tumor samples compared with adjacent normal tissues." (PMID 37993428, 2023). "Moreover, knockdown of FTX inhibited the tumor growth and increased the expression levels of miR-513b-5p and apoptosis-related proteins in vivo." (PMID 33736615, 2021). "A recent study by Zhao and coworkers demonstrated that the expression of miR-192-5p is downregulated in CRC, and the knockdown of miR-192-5p can compromise the tumor suppressive effect of the sh-lncRNA, FTX, indicating the anti-tumor effect of miR-192-5p in CRC." (PMID 33708127, 2021). "In addition, knockdown of FTX significantly reduced the number of EdU positive cells in tumor tissues (p < 0.05), while co-injection obviously attenuated its inhibitory effect (p < 0.05)." (PMID 34720057, 2021). "The tumors formation were significantly suppressed by FTX increasing, while GdCl3 treatment could reverse the inhibitory effect of FTX increasing on tumor formation." (PMID 32595415, 2020). "The expression of FTX was significantly decreased in tumor tissues." (PMID 32595415, 2020). "LncRNA FTX acts as a negative regulator of the Wnt/β-catenin signaling by inhibiting HCC cell epithelial-mesenchymal transition and repressing tumor invasion and metastasis." (PMID 37508414, 2023). "In contrast with reported role of FTX as a promoter of oncogenesis in different tumors, in lung and HCC FTX can work as a tumor suppressor, again via ceRNA activity." (PMID 35054794, 2022). "The great weight coefficient given by these gender-related lncRNAs were obvious in small size tumor (G1/G2 < 5 cm), and was rapidly lost when the tumor became malignant (G3/G4, > 5 cm) and the expression of XIST and FTX were significant inhibited." (PMID 34557343, 2021). "Then, we checked FTX mRNA levels in collected clinical samples from NSCLC patients, and real‐time PCR data suggested that 74% (37/50) of NSCLC tumour samples exhibited reduced FTX expression compared to adjacent normal tissues." (PMID 32176463, 2020). "CANT1 acts as a tumor suppressor, inhibiting both cell migration and tumorigenesis of UM, for which it is able to trigger and modulate a non-coding cascade (CANT1–JPX/FTX–XIST)." (PMID 33053887, 2020). "Inhibition of JPX/FTX transmits the signal to XIST, decreasing its expression levels and completing the sequence that ultimately leads to both activation of tumor growth and stimulation of metastatic capacity." (PMID 33053887, 2020). "Downregulation of FTX has an inhibitory effect on the viability and metastasis of CRC cells, which may slow the tumor progression." (PMID 38796816, 2024). "The lncRNA FTX was downregulated and the lncRNA SNHG20 was upregulated in NAFLD-related HCC tumor tissues, and FTX supplement and SNHG20 silencing inhibited the conversion of NAFLD to HCC, which prompted out interest in explorng its potential as a future HCC risk predictor." (PMID 36979495, 2023). "Given that MCL patients with abundant tumor-infiltrating CD8+ T-cells and low levels of FTX or PCA3 lncRNA can predict poorer overall survival, it may be possible to include WTS analysis during diagnosis to improve MCL prognostication." (PMID 36359790, 2022). "In addition, IHC results showed that, compared to the control group, the number of Ki-67 positive cells in PC tumor tissues of LV-FTC group was markedly decreased, suggesting that silencing of FTX inhibited the growth of PC cells in vivo." (PMID 33736615, 2021).
tumor (continued). "Importantly, increasing of FTX inhibited HCC tumor growth, improved liver damage and promoted M1 polarization of KCs during NAFLD conversion to HCC, while these effects of FTX were reversed by inactivating of KCs." (PMID 32595415, 2020). "Moreover, a long non-coding RNA, FTX is shown to sponge miR-200a thereby impairing the inactivation of miR-200a target, FOXA2, a transcription factor, acting as a tumor suppressor that attenuates tumor cell proliferation, migration, and invasion." (PMID 41271627, 2025). "When tumor-infiltrating CD8+ T-cell abundance was analyzed together with each of these transcripts, we observed that high CD8+ T-cells with low expression levels of FTX lncRNA predicted poorer overall survival compared to CD8+ T-cell ratio when all or diagnostic MCL cases were analyzed." (PMID 36359790, 2022). "In particular, FTX interacted with DHX9 and Dicer and regulated A-to-I RNA editing and miRNA expression; miR-374b and miR-545 repressed tumor suppressors PTEN and RIG-I to increase proto-oncogenic PI3K-AKT signaling; miR-421 may have an autoregulatory effect on miR-374b and miR-545." (PMID 35054794, 2022). "For instance, silencing lncRNAs such as MEG3, FTX, and MIAT in tumor-infiltrating myeloid or T cells, or enhancing expression of pro-inflammatory lncRNAs like NEAT1 or MIR17HG in T cells, may reduce immunosuppression, promote infiltration, and enhance activation of anti-tumor immunity." (PMID 40527978, 2025). "Moreover, FTX suppression in THP-1 cells increases NF-κB activity and pro-inflammatory cytokine expression, suggesting that a reduction in FTX might accelerate tumor progression by enhancing inflammation in the tumor microenvironment (TME)." (PMID 38473915, 2024).
cancer (29 papers, 2019 to 2025). A tumor composed of atypical neoplastic, often pleomorphic cells that invade other tissues. "In fact, a reduced expression of LncRNA FTX correlates with the development of cancer and is associated with worse prognosis, whereas higher LncRNA FTX expression correlates with a longer survival." (PMID 37508414, 2023). "One lncRNA module was confirmed to be associated with cancer metastasis, and nine hub lncRNAs, namely FTX, AC005261.1, NORAD, LINC01578, AC004542.2, ZFAS1, EBLN3P, THUMPD3-AS1, and GAS5, were discovered." (PMID 36514044, 2022). "This meta-analysis synthesized existing data to clarify the association between FTX with cancer prognosis." (PMID 33398336, 2021). "LncRNA five prime to Xist (FTX), located at X-chromosome inactivation center, is associated with the pathogenesis of multiple diseases, such as epilepsy, heart disease, and cancers." (PMID 33817286, 2020). "Additionally, a positive association between FTX and advanced stage of cancers was found (p < 0.05)." (PMID 35027040, 2022). "Aberrant expression of FTX has been linked to the cell progression of various cancers." (PMID 33817286, 2020). "PDPN+ cancer-associated fibroblasts were shown to transfer exosomal lncRNA FTX to OSCC cells, activating an FTX/FEN1/ACSL4 axis that suppresses ferroptosis and enhances cell motility, linking CAF signaling with ferroptosis resistance and poor prognosis." (PMID 41227330, 2025). "Lnc-FTX functions as an oncogene across various cancers, facilitating the malignant behaviors of cancer cells." (PMID 40084261, 2025). "Current studies on FTX have mainly focused on its regulation of X chromosome inactivation and the progression of various malignant tumors, while its role in pluripotency regulation of stem cells has not yet been reported." (PMID 37106382, 2023). "Due to its role, LncRNA FTX is involved in the development and progression of several types of cancer." (PMID 37508414, 2023). "The results of analysis using TCGA dataset revealed that FTX was differentially expressed in cancers including CESC, LAML, OV, PCPG, UCEC and UCS as compared with normal tissues." (PMID 35027040, 2022). "Based on our data, we revealed for the first time that the expression levels of FTX were notably elevated in RB tissues and cancer cell lines." (PMID 34720057, 2021). "For example, lncRNA FTX is dysregulated in GC, and FTX promotes cancer cell proliferation, migration, and invasion." (PMID 34037089, 2021). "To further investigate the mechanism of FTX, we assessed the expression of miR-320a in cancer cell lines and RB tissues." (PMID 34720057, 2021). "The role of FTX in cancers was evaluated by pooled odds ratios (ORs) and hazard ratios (HRs) with 95% confidence intervals (CIs)." (PMID 33398336, 2021). "Nonetheless, the effects of FTX expression on the development and prognosis of cancer are still controversial." (PMID 33398336, 2021). "In recent years, changes in FTX expression in different types of cancers and the influence of FTX expression in cancer have attracted much attention." (PMID 33398336, 2021). "In the present study, we found that the expression levels of FTX were notably elevated in RB tissues and cancer cell lines." (PMID 34720057, 2021). "Accumulating research has clarified that FTX is a significant predictor of different diseases, including cancers." (PMID 33817286, 2020). "LncRNA FTX transcript, XIST regulator (FTX) has been reported to regulate the biological behaviors of some cancers." (PMID 32226311, 2020). "Overall, considering the emerging roles played by FTX in cancer, we believe that our finding can shed new light on the regulation of this lncRNA in GBM." (PMID 33066171, 2020). "LncRNA FTX is tied to cancer proliferation and abnormal metabolism." (PMID 39928309, 2025). "FTX has been reported to be involved in the tumorigenesis of multiple cancer types." (PMID 37218885, 2023).